PPARG (peroxisome proliferator activated receptor gamma)
Diseases named in the same sentence as PPARG in open-access papers (continued):
Sharing a sentence is not in itself a finding about the gene and the disease.
cancer (continued). "Inhibition of angiogenesis may contribute to the mechanism by which PPARγ agonists halt the cancer process." (PMID 23024650, 2012). "A large body of literature has demonstrated that direct activation of PPARγ in a variety of cancer cells leads to inhibition of growth, decreased invasiveness, reduced production of proinflammatory cytokines, and in many cases promotion of a more differentiated phenotype." (PMID 22934105, 2012). "Nonetheless, the speculations concerning PPARα/β relative expression and function in cancer cells are further based on their opposite to PPARγ physiological roles." (PMID 22448166, 2012). "Indeed, data from our laboratory indicate that macrophage-specific PPARγ plays a critical role in the ability of cancer cells to educate macrophages into an alternatively activated phenotype." (PMID 22934105, 2012). "However, cancer stem cells have reduced the expression of PPARγ, allowing cells to escape from the control of the normal cell cycle." (PMID 23316217, 2012). "Both, PPARγ-dependent and -independent pathways that contribute to inhibition of cancer cell growth may be beneficial for cancer chemotherapy." (PMID 22685453, 2012). "Activation of PPARγ leads to a reduction of adhesion and motility in some cancer models." (PMID 22761953, 2012). "The pro-apoptotic properties of PPARγ and its ligands may also favor the commitment of cancer cells towards apoptosis." (PMID 22654896, 2012). "Furthermore, PPARγ induces apoptosis directly through Fas, resulting in an inhibitory effect on carcinoma." (PMID 23316217, 2012). "PPARγ is a highly conserved nuclear receptor expressed throughout the body and is over expressed in many cancers, including ovarian and breast cancer, making it a potentially important player in the development of cancer." (PMID 21283708, 2011). "Reports indicate that transcription factor PPARγ inhibits the expression of several MMPs by antagonizing the activities of AP-1 and NFκB and has recently been considered as an important target for development of new drugs for cancer therapy." (PMID 21283694, 2011). "Moreover, based on our in vitro studies we propose that PPARγ in macrophages is critical for the conversion of macrophages into an alternatively activated phenotype in the presence of cancer cells which has been shown to promote metastasis." (PMID 22145026, 2011). "Taken together these data strongly suggest that PPARγ agonists inhibit cancer cell invasion through a PPARγ-independent pathway and that as our data suggests PPARγ itself could in fact be promoting invasive capacity." (PMID 22194735, 2011). "However, a role for PPARγ agonists in miRNA-based therapeutic strategies to treat cancer awaits further clarification by new research endeavors." (PMID 20204067, 2010). "More recent studies indicate a new and emerging role of PPARγ in regulating growth of cancer cells." (PMID 21144036, 2010). "Recent studies have suggested that PPARγ has an inhibitory effect on cancer cell growth and might inhibit cell growth and induce apoptosis in adenocarcinomas, as well as affect tubulin formation in vitro." (PMID 20814432, 2010). "In that PPARγ agonists inhibit both NF-κB- and Stat3-mediated transactivation of target genes and both of these transcription factors play a prominent role in cancer progression (see Section 2.8 and references therein), it is a likely extension to consider a role for PPARγ agonists to target CSCs." (PMID 20204067, 2010). "When considering the use of PPARγ agonists as adjuvant or combination therapy in hematological malignancies, it will be important to design appropriate preclinical studies that assess the severity of these side effects in the context of each type of cancer." (PMID 20204067, 2010).
cancer (continued). "Our group has long been interested in the study of nuclear hormone receptor targeted therapy for the treatment of poorly differentiated cancer with a primary focus on the retinoid receptors and peroxisome-proliferator activated receptor gamma (PPARγ) as novel therapeutic targets." (PMID 19267912, 2009). "This is potentially significant, since PPARγ is also highly expressed in many cancers and therefore may play a role in inhibiting apoptosis via Pim3 expression." (PMID 19300518, 2009). "While PPARγ activation shows beneficial anti-inflammatoryeffects in the pancreas, the consequences of such activation in patients withpancreatic cancer are unknown." (PMID 19125181, 2008). "The differential activation of PPARγ and PPARγ-regulated genes by specific dietary fatty acids may be central to their distinct roles in cancer." (PMID 18769551, 2008). "Many literatures reported that PPARγ possesses an anticarcinogenic effect incolorectal cancer." (PMID 18551182, 2008). "Carotenoids are another class of phytochemicals foundto activate PPARγ in cancer cells." (PMID 18779870, 2008). "This review will highlight recent research advances on PPARγ and apoptosis in cancer." (PMID 18615184, 2008). "However, as emphasized byarticles in this special issue of PPAR research, in some situations, like incolon cancer models, PPARγ agonists can have tumorpromoting effects." (PMID 18509497, 2008). "Indeed, its effectson cancer cells are more potent than several PPARγ agonists, including ciglitazone androsiglitazone." (PMID 19190780, 2008). "Accordingly, targetingPPARs, especially PPARγ for cancer chemoprevention and therapy may proveto be very effective and will remain an interesting research topic." (PMID 18615184, 2008). "This datasuggest that cancer-preventive functions of PPARγ activators may be related to someextent to a parallel induction of GSTA2." (PMID 18779870, 2008). "Also, the observation that combinations of PPARγ agonist and antagonist compounds result inadditive antiproliferative effects in various cancer cell lines isconsistent with this mechanism." (PMID 18779871, 2008). "Moreover, troglitazone derivativeswhich are unable to activate PPARγ suppress cancer cell proliferationsimilar to troglitazone, giving further evidence that the antiproliferativeeffects of troglitazone are at least in part PPARγ-independent." (PMID 18725982, 2008). "PPARγ is known to be expressed in various organs, including adipose tissue, mammary glands, smallintestine, lung, colon, and stomach, andis also upregulated in various types of cancer cells." (PMID 18483618, 2008). "Peroxisome proliferator-activated receptor-γ (PPARγ) and retinoic acid X-receptor (RXR) heterodimer, which regulates cell growth and differentiation, represses the TGFβ1 gene that encodes for the protein involved in cancer biology." (PMID 18615188, 2008). "Moreover, several bioactive natural products with cancer protecting potential are shown to operate through activation of PPARγ." (PMID 18779870, 2008). "The involvement of PPARα and PPARγ in cancer pathogenesishas been reviewed extensively." (PMID 19197366, 2008). "Although PPARγ plays an important part in the transmission of insulin responses andphysiological diet, little direct evidence exists relating these factors toPPARγ activation and the risks of thedevelopment of cancer." (PMID 18596912, 2008). "PPARγ is highly expressed in human colon tumorspecimens and cancer cell lines." (PMID 19125177, 2008). "Ligands for PPARγ reportedly induce cell cyclearrest in various cancer cells." (PMID 18725985, 2008). "More recent results indicating that PPARγ activation mayattenuate inflammatory responses and cancer progression have led to extensiveinvestigation into the role of this protein in inflammation and carcinogenesis." (PMID 18769553, 2008). "The prediction would be that in the rat urothelium in vivo, PPARα activation may providecancer initiation and PPARγ activation cancer promotion signals." (PMID 19197366, 2008).
cancer (continued). "Itis, therefore, clear that the regulation of angiogenic factors by PPARα and PPARγ may bedetermined by cell and cancer type and the experimental models used." (PMID 19043612, 2008). "In addition to its function as a regulator of adipocytes differentiation, PPARγ is expressed by several other tissues, and is involved in a number of pathological processes, such as inflammation and cancer." (PMID 19002260, 2008). "We suggest that TZD therapy, bystimulating PPARγ-dependent downregulation of CXCR4 on cancer cells, may slowthe rate of metastasis and may impact beneficially on disease progression." (PMID 18779872, 2008). "Although the differentiating andantiproliferative effects of PPARγ activation form the basis for evaluating PPARγ ligands for cancer therapy, theanti-inflammatory effects of PPARγ may also be relevant to coloncarcinogenesis." (PMID 19125177, 2008). "Induction of apoptosis may involve the tumornecrosis factor-related apoptosis-inducing ligand (TRAIL)-induced apoptosis insome cancer cell lines; these effects appear to be mediated through PPARγ-independent pathways." (PMID 18509496, 2008). "Finally, PPARγ activation can induce growth arrest, differentiation, or apoptosis in many cancer cells." (PMID 19125181, 2008). "Another study showedthat anticancer effects were associated with reductions in tubulin levels (avalidated cancer-related target), but this was not mediated by PPARγ, PPARδ, or the proteasome." (PMID 18779871, 2008). "In one in vivo study, however, the PPARγ agonist pioglitazone prevented cancer in ahamster model." (PMID 19125181, 2008). "As we continue to elucidatethe molecular mechanisms of PPARγ in the regulation of cancer formationand development, combining PPARγ agonists with other targeted anticanceragents may be an effective strategy for chemoprevention and treatment ofvarious cancers." (PMID 18615184, 2008). "PPARγ-independent growth inhibitory andantimetastatic effects of several antagonist compounds were shown in both in vitro and in vivo studies using threecolon carcinoma cell lines." (PMID 18779871, 2008). "Samples of adjacent nonneoplastic colonicmucosa from the same patients were also collected for comparison.In 19 of 24 patients, PPARγ protein content was higher incancer specimens than in mucosa specimens, showing thatPPARγ was generally increased in cancer versus mucosa." (PMID 17389773, 2007). "Indeed, among 20 investigated cancer tissue samples, PPARγ increased between 1.5- and 4-fold in 35% (n = 7), while we noted a 1.5- to 6-fold decrease in 25% (n = 5)." (PMID 17767717, 2007). "Furthermore, we cannot explain the differences found between the anti-cancer effect of PPARγ activation in vitro and our results." (PMID 17584937, 2007). "Previously, TGZ was shown to induce cancer cell apoptosis by non-PPARγ mechanisms." (PMID 18021457, 2007). "Moreover, 15d-PGJ2 has been shown to induce apoptosis of cultured cortical neurons, endothelial cells, hepatic myofibroblasts, granulocytes and cancer cells, through both PPARγ-dependent and PPARγ-independent mechanisms." (PMID 17634127, 2007). "The fact that we observe an association with cancer for some PPARγ agonists (TZDs), but not others (sulfonylureas;) suggests the notion of PPARγ-independent mechanisms in the association between TZDs and cancer." (PMID 17584937, 2007). "This enzyme might mediate the promotion of colon carcinogenesis by metabolic disorders and inflammation and several lines of evidence indicate that COX-2 might be regulated by PPARγ and RARβ activation in cancer cells although the mechanism is unclear." (PMID 17767717, 2007). "New evidence suggests PPARγ may play a role in the differentiation of epithelia, which is an exciting prospect in the field of cancer research." (PMID 16519808, 2006). "However, it has recently been demonstrated that PPARγ ligands can exert PPARγ-independent biological responses including growth arrest and apoptosis in selected carcinoma types." (PMID 16519808, 2006).
cancer (continued). "The growth inhibitory and differentiation roles of PPARγ have been shown in several cancers." (PMID 15583697, 2005). "In cancer biology, PPARγ is the most intensively studied PPAR isoform." (PMID 15583697, 2005). "Besides, no evident relationship between anticancer efficacy and the expression of PPARγ in cancer cells or the binding affinity of thiazolidinediones to PPARγ has been established." (PMID 15467764, 2004). "Subsequent studies indicated that PPARγ agonists, at concentrations of 1–10 μM, may induce growth inhibition in a variety of cancers, including cancers of breast, colon, and prostate." (PMID 15467764, 2004). "The capacity of PPARγ to promote differentiation, cell cycle withdrawal and apoptosis has encouraged extensive investigation of its potential anticancer activity in multiple types of human cancer (see Introduction)." (PMID 12454768, 2002). "However, direct evidence of TFPI2 activating PPARγ specifically in cancer cells remains limited." (PMID 40361374, 2025). "Together, these findings highlight the multifaceted relationship between PPARγ activity and mTOR signaling, suggesting that modulation of this axis could have both therapeutic potential and context-dependent metabolic consequences in cancer cachexia." (PMID 41476922, 2025). "On the one hand, activation of PPARγ by synthetic agonists such as TZDs or natural ligands like resveratrol and curcumin can inhibit cell proliferation, induce differentiation, and promote apoptosis across various cancer types including breast, colorectal, and lung malignancies." (PMID 41476922, 2025). "Furthermore, a high expression level of PPARγ was identified as a predictor for poor prognosis for OSC as well as a potential biomarker for predicting the recurrence of OSC based on multiomic pan-cancer analysis using TCGA." (PMID 40429934, 2025). "However, their protective effect in other cancers may be explained by the activation of the peroxisome proliferator-activated receptor gamma (PPAR-γ)." (PMID 40290515, 2025). "Therefore, the restoration of adipose tissue homeostasis and PPARγ regulation by Bergacyn® could lessen inflammation and metabolic signals involved in certain cancers." (PMID 40732979, 2025). "Therapeutic intervention that specifically targets the peroxisome proliferator-activated receptor gamma (PPARγ) and its downstream response element, in response to lipid metabolism, has been found to promote the growth of tumors and has shown significant clinical advantages in cancer patients." (PMID 39148124, 2024). "This review explores the molecular mechanisms by which the Cladosporol/PPARγ complex may simultaneously interfere with a dysregulated lipid metabolism and cancer promotion and progression, highlighting the potential therapeutic benefits of Cladosporols for human health." (PMID 39199386, 2024). "Therefore, the combination of MEK inhibitors and PPARγ agonists induces adipogenesis, which may lead to the transdifferentiation of cancer cells into true adipocytes." (PMID 37935080, 2024). "Furthermore, PPARγ may also contribute to a reduction in cancer phenotypes and characteristics induced by serotonin." (PMID 38741139, 2024). "Several studies demonstrated that both PPARα and PPARγ could be involved in cancer apoptosis." (PMID 37237519, 2023). "Hence, PPARG has the potential to serve as a molecular marker for cancer." (PMID 38044948, 2023). "In murine models of cancer, depleting PPARγ from the adipocyte, immune, endothelial, and perivascular compartments animal is an attractive next step toward understanding the relative contribution of stromal cell types to the antitumor effect of PPARγ activation." (PMID 37816052, 2023). "Consequently, PPARγ holds promise as a potential target for evaluating cancer prognosis." (PMID 38044948, 2023). "Notably, the role of PPARγ in cancer progression is still in debate." (PMID 36998980, 2023). "In this context, PPARγ targeting could represent a strategy for cancer treatment." (PMID 38137407, 2023).
cancer (continued). "The role of PPARg in cancers remains controversial and may depend on the cancer type and stage." (PMID 36681687, 2023). "PPARγ might inhibit early primary cancer growth, but fuels advanced-stage metastatic formation." (PMID 35954274, 2022). "Moreover, PPARγ could potentially discriminate the patients from the controls also malignant tumors from benign tumors with significant sensitivity and specificity." (PMID 35922782, 2022). "However, the upstream role of PPARγ in cancer biology is poorly characterized." (PMID 35449157, 2022). "Finally, our results may serve as a motivation for further investigations on matcha tea induced PPARγ alterations in cancer cell or animal models." (PMID 35079875, 2022). "In addition, it has been shown that PPARG agonists also enhance the activity of Histone deacetylase Inhibitors (HDACi), which may act as epigenetic regulators to exert anti-cancer effects." (PMID 36425653, 2022). "However, increased PPARγ expression has been found to control other pathways that could induce cancer development and progression." (PMID 36358965, 2022). "Moreover, a mounting body of studies has suggested that the activation of PPARγ in cancer cells could induce apoptotic signals by altering the balance between the expression level of pro‐ and anti‐apoptotic target genes." (PMID 34549887, 2021). "While synthetic thiazolidinedione-class PPARγ agonists were initially used as anti-diabetic agents, PPARγ ligands have more recently been examined as potential therapeutic or chemoprevention targets for dermatologic conditions, including cancer and inflammatory dermatoses." (PMID 34445339, 2021). "Several mechanisms accounting for the same are: the downstream effects of PPARγ-mediated metabolism (by altering the microenvironment that allows the cells to autonomously synthesize nutrients through lipid accumulation and angiogenesis) and increased cancer cell migration and invasion." (PMID 34535145, 2021). "PPARγ agonists may also act as negative regulators of cancer growth by the interaction with the IGF system and its down-stream pathways, such as mitogen-activated protein kinase (MAPK), phosphoinositide 3-kinase (PI3K), and the mechanistic target of rapamycin (mTOR) pathways." (PMID 34067944, 2021). "However, in practice, the induction of death in cancer cells is usually caused by the application of PPARγ ligands rather than by the upregulation of PPARγ itself." (PMID 34557159, 2021). "Therefore, we speculated that HSYA may exert anti-cancer effect on CRC via activating PPARγ/PTEN/Akt signaling." (PMID 34889713, 2021). "In addition, we will address the yet partly undefined role of PPARγ fusion proteins in cancer." (PMID 33716977, 2021). "Therefore, we proposed that PPARγ may be a promising therapeutic target in the prevention and treatment of cancer cachexia." (PMID 34093209, 2021). "On the other hand, antiproliferative effects of TZDs on breast, prostate, and other types of cancer, have been evidenced in malignant human cell lines and rodents, together with the results that combination with PPARγ agonists may improve some cancer therapies." (PMID 34681797, 2021). "Further in vivo studies related to cancer and mechanistic studies assessing the role of PPARγ agonists are required; nevertheless, this study suggests that FA could potentially be developed as an anticachetic supplement and an anticancer agent with few known side effects." (PMID 34502316, 2021). "Peroxisome proliferator-activated receptor gamma (PPARγ), belonging to the nuclear receptor superfamily, is a ligand-dependent transcription factor involved in a variety of pathophysiological conditions such as inflammation, metabolic disorders, cardiovascular disease, and cancers." (PMID 32937951, 2020).